CHGA (chromogranin A)
Description:
[Pancreastatin]: Strongly inhibits glucose induced insulin release from the pancreas. [Catestatin]: Inhibits catecholamine release from chromaffin cells and noradrenergic neurons by acting as a non-competitive nicotinic cholinergic antagonist. Displays antibacterial activity against Gram-positive bacteria S.aureus and M.luteus, and Gram-negative bacteria E.coli and P.aeruginosa. Can induce mast cell migration, degranulation and production of cytokines and chemokines. Acts as a potent scavenger of free radicals in vitro. May play a role in the regulation of cardiac function and blood pressure. [Serpinin]: Regulates granule biogenesis in endocrine cells by up-regulating the transcription of protease nexin 1 (SERPINE2) via a cAMP-PKA-SP1 pathway. This leads to inhibition of granule protein degradation in the Golgi complex which in turn promotes granule formation.
Synonyms: CgA; PHE5; PHES
Tractability: Antibody: UniProt places it where antibodies can reach, with high confidence; its Gene Ontology location is reachable by antibodies, with high confidence; UniProt predicts a signal peptide or a membrane-spanning region. PROTAC: its protein half-life has been measured.
Gene: Protein-coding gene on chromosome 14 (92,922,630 to 92,935,293, forward strand). Ensembl gene ENSG00000100604.
Subcellular location: Secreted (Serpinin); Cytoplasmic vesicle, secretory vesicle; Cytoplasmic vesicle, secretory vesicle, neuronal dense core vesicle; Secreted
Subcellular location (Human Protein Atlas): Vesicles
Pathways (Reactome):
Immune System: Antimicrobial peptides
Gene Ontology:
Biological process: defense response to Gram-negative bacterium; defense response to Gram-positive bacterium; mast cell activation; mast cell chemotaxis; mast cell degranulation; negative regulation of catecholamine secretion; adenylate cyclase-activating adrenergic receptor signaling pathway; defense response to bacterium; innate immune response; negative regulation of insulin secretion; positive regulation of cardiac muscle contraction; positive regulation of dense core granule biogenesis; positive regulation of phospholipase C-activating G protein-coupled receptor signaling pathway; positive regulation of relaxation of cardiac muscle; regulation of blood pressure; regulation of the force of heart contraction
Cellular component: extracellular region; perinuclear region of cytoplasm; chromaffin granule; neuronal dense core vesicle; secretory granule; transport vesicle
Genetic constraint (gnomAD): Loss-of-function variants: 41 observed, 50.71 expected, observed/expected ratio (o/e) 0.81, 90% interval 0.63 to 1.05. The upper end of that interval is the gene's LOEUF score, 1.05, which puts it in group 4 of 6, group 1 being the genes least tolerant of losing a copy. Missense variants: 561 observed, 548.85 expected, observed/expected ratio (o/e) 1.02, 90% interval 0.95 to 1.1. Synonymous variants: 240 observed, 214.52 expected, observed/expected ratio (o/e) 1.12, 90% interval 1.01 to 1.25.
Homologues: Orthologues: chimpanzee CHGA (100% identical), macaque CHGA (90% identical), pig CHGA (77% identical), dog CHGA (73% identical), mouse Chga (68% identical), rat Chga (68% identical), guinea pig CHGA (63% identical), tropical clawed frog chga (33% identical), zebrafish chga (24% identical). Paralogues in human: CHGB (23% identical).
Diseases named in the same sentence as CHGA in open-access papers:
CHGA is named in the same sentence as 267 diseases in open-access papers, as found by Europe PMC text mining. Sharing a sentence is not in itself a finding about the gene and the disease. The quoted sentences say what the papers report.
neuroendocrine tumors (178 papers, 1998 to 2026). "Recently, the marker INSM1 has been identified as another promising marker for neuroendocrine tumors, potentially improving diagnostic accuracy when combined with synaptophysin and chromogranin A." (PMID 40735045, 2025). "Chromogranin A, neutrophils and platelets-to-lymphocyte ratio were associated with disease progression during systemic treatment in gastroenteropancreatic neuroendocrine tumors." (PMID 35674592, 2022). "Chromogranin A is a protein produced and released by tumor cells and a good marker generally associated with all neuroendocrine tumors." (PMID 35372578, 2022). "The laboratory variables chromogranin A, neutrophils, and platelets-to-lymphocyte ratio are associated with disease progression during systemic treatment for gastroenteropancreatic neuroendocrine tumors." (PMID 35674592, 2022). "We also studied if WNT2 expression was associated with expression of enteroendocrine cell/neuroendocrine tumor markers chromogranin A (CHGA) and synaptophysin (SYP)." (PMID 34274970, 2021). "Expression of CHGA has been reported to be associated with prognosis in colorectal cancer, and is generally recognized as the main biomarker for neuroendocrine neoplasms." (PMID 34868990, 2021). "In recent years, the reported incidence of neuroendocrine tumors has been increasing, probably due to the better sensitivity of diagnostic tests and more frequent staining of chromogranin A and synaptophysin during the histopathological examination." (PMID 34917031, 2021). "Chromogranin A (CgA) is the most widely accepted biomarker for neuroendocrine tumors (NET) but its diagnostic accuracy is dependent on tumor type and the use of proton-pump inhibitors (PPI)." (PMID 32887459, 2020). "These include CHGA (also associated with neuroendocrine tumors), CFH, SPP1, and an immunoglobulin-like receptor." (PMID 30678299, 2019). "In previous decades, chromogranin A (CgA) has been demonstrated to be the most promising biomarker for the diagnosis of neuroendocrine tumors (NETs), but its diagnostic value is still controversial." (PMID 25894842, 2015). "Serum chromogranin-A (Cg-A) appears to be the most useful diagnostic marker in the diagnosis of gastric carcinoids, as well as the rest of the neuroendocrine tumors." (PMID 23316222, 2012). "Furthermore, genes encoding canonical markers of neuroendocrine tumors—including CHGA (chromogranin A), SYP (synaptophysin), NCAM1 (CD56), and ENO2 (neuron-specific enolase)—were all differentially higher in s3 tumors." (PMID 36731467, 2023). "Chromogranin-A (CgA), commonly expressed in neuroendocrine tumors, may be associated with poorly differentiated PCa." (PMID 29312648, 2017). "CHGA protein was thought to be a tumor marker in neuroendocrine tumors (NETs), but high expression of CHGA was also found in several other types of solid tumor, such as small cell lung cancer, and higher expression of CHGA was associated with higher pathological stage in prostate cancer." (PMID 23599765, 2013). "Notably, the expression of genes found to be typically active in neuroendocrine tumors (Hofsli gene signature) were also significantly diminished in 424GC cells, including genes encoding neuroendocrine markers such as chromogranin A, dopa decarboxylase (DDC) and TPH1." (PMID 22253802, 2012). "Histopathological examination with immunohistochemistry confirmed a well-differentiated neuroendocrine tumor with strong chromogranin A positivity." (PMID 41869226, 2026). "Chromogranin A (CgA), a glycoprotein prohormone, modulates various processes including angiogenesis and innate immunity, and its higher levels are detected in neuroendocrine tumors and inflammatory disorders." (PMID 41753254, 2026). "Both populations were also characterised by expression of chromogranin/secretogranin neuroendocrine tumour marker genes (e.g. CHGA, SCGN)." (PMID 40438247, 2025).
neuroendocrine tumors (continued). "Chromogranin A is another sensitive marker for neuroendocrine tumours and is also elevated in the presence of PGLs." (PMID 40352976, 2025). "A moderate correlation was observed between MTV on [18F]SiTATE-PET/CT and serum chromogranin A levels, with chromogranin A being commonly used as a tumor marker for neuroendocrine tumors." (PMID 40445313, 2025). "Among morphologically non‐neuroendocrine tumours, the number of cases showing positivity for at least two neuroendocrine markers was the same for synaptophysin/chromogranin A compared to synaptophysin/INSM1." (PMID 39526928, 2025). "According to the 2023 European Guidelines for Neuroendocrine Tumors of the Digestive System, approximately 60% of patients have elevated chromogranin A and NSE in their blood." (PMID 40958335, 2025). "In humans, chromogranins, particularly chromogranin A and SCGN, are associated with secretory granules in neuroendocrine cells, and are biomarkers of neuroendocrine tumours and a variety of diseases." (PMID 40438247, 2025). "According to the WHO neuroendocrine tumors of the thymus typically exhibit strong, diffuse immunoreactivity for at least one neuroendocrine marker, such as chromogranin A, synaptophysin, CD56, and neuron-specific enolase (NSE), in more than 50% of tumor cells." (PMID 40843719, 2025). "The diagnosis of neuroendocrine tumors is characterized by the detection of immunohistochemical markers: synaptophysin, chromogranin A, and neuron-specific enolase." (PMID 39996224, 2025). "Neuroendocrine tumor cells contain chromogranin-A, synaptophysin, and neuron-specific enolase and can secrete hormones." (PMID 41281106, 2025). "AFP was within normal range (3.6 ng/mL), while chromogranin A was markedly elevated at 114.9 ng/mL, heightening suspicion for a neuroendocrine tumor." (PMID 41181755, 2025). "Neuroendocrine tumors: small to medium-sized hyperchromatic cells; confirmed via immunohistochemistry (e.g., chromogranin A)." (PMID 41440485, 2025). "While chromogranin A (CgA) is a widely used biomarker for neuroendocrine tumors, its role in diagnosing ANETs is limited, particularly in early-stage tumors." (PMID 40271189, 2025). "Chromogranin A (CgA) is a protein found in cells of neuroendocrine origin and has been the most widely used biomarker for neuroendocrine neoplasms in general to date." (PMID 37770647, 2024). "In thoracic neuroendocrine tumor studies, serum chromogranin A (CgA) has been predominantly discussed in the context of L-NETs, albeit with limited sensitivity and prediction accuracy." (PMID 39061142, 2024). "The management of neuroendocrine neoplasms (NENs) involves the measurement of serum chromogranin A (s-CGA), serum neuro-specific enolase (s-NSE), and urinary 5-hydroxindolacetic acid (5-HIAA)." (PMID 39596382, 2024). "The histopathological findings showed a well-differentiated neuroendocrine tumor with positive synaptophysin and chromogranin A immunostains." (PMID 38854200, 2024). "PGL and neuroendocrine tumors from different organs can share similarities in their nested structure and expression of neuroendocrine markers such as chromogranin A and synaptophysin." (PMID 39507200, 2024). "Immunohistochemical markers such as chromogranin A (CgA) and synaptophysin (Syn) are crucial for confirming neuroendocrine differentiation of tumors and are indispensable in the diagnosis of neuroendocrine tumors." (PMID 39507752, 2024). "Immunohistochemical analysis revealed that the neuroendocrine tumor cells were positive for chromogranin A, synaptophysin, and CD56." (PMID 37306825, 2023). "CHGA is a 439‐residue‐long protein in the secretory granules of many normal and neuroendocrine tumour cells." (PMID 37246623, 2023). "Subsequent immunohistochemistry analysis on these CDX tumors show positivity for commonly used markers for SCLC diagnosis: CD56, synaptophysin and chromogranin A, demonstrating the stability of the patient’s neuroendocrine tumor lineage." (PMID 36869231, 2023).
neuroendocrine tumors (continued). "Neuroendocrine neoplasms are diagnosed by immunostaining, such as specific stains for synaptophysin, chromogranin A and INSM1." (PMID 37027114, 2023). "Our analysis also tried to find a link between serum levels of common neuroendocrine tumor markers such as chromogranin A (CgA), serotonin, and 5-hydroxy indoleacetic acid (5-HIAA) and bone metastases in PanNETs." (PMID 37510802, 2023). "In contrast, neuron-specific enolase and chromogranin A, two clinically used markers for neural/neuroendocrine tumors consistently exhibit positive correlations with NE scores across studies." (PMID 37378310, 2023). "Serum levels of chromogranin A are elevated in different neuroendocrine tumors, including carcinoids, pancreatic tumors, pheochromocytoma, paraganglioma, and neuroblastoma." (PMID 38069002, 2023). "As a neuroendocrine tumor, neuroendocrine markers such as chromogranin A, synaptophysin, CD56, neuron‐specific enolase usually confirm the diagnosis." (PMID 36950672, 2023). "IHC predominantly showed weak or negative staining for markers such as TTF‐1, CK5/6, p40, synaptophysin, chromogranin A, and CD56, which are often associated with adenocarcinoma, squamous cell carcinoma, and neuroendocrine tumors." (PMID 38124509, 2023). "The remaining specimen showed proliferation of epitheloid cells that were found by immunohistochemical analysis to be positive for chromogranin A and synaptophysin, consistent with a neuroendocrine neoplasm." (PMID 37306825, 2023). "Both PDX tumors stained positive for the neuroendocrine tumor markers chromogranin A (CgA) and synaptophysin (SYP), but only the NEC913 PDX tumor stained positive for somatostatin receptor 2 (SSTR2)." (PMID 35454817, 2022). "Neuroendocrine tumors are identified through immunohistochemical staining for common markers including chromogranin A/B, synaptophysin and neuron specific enolase (NSE)." (PMID 36440195, 2022). "CHGA is a secreted glycoprotein produced by neuroendocrine cells and as such, it has been well established as a marker of neuroendocrine tumors." (PMID 35241690, 2022). "Immunohistochemistry showed ALK, EMA, and AE1/AE3 immunoreactivity suggesting ALK-rearranged renal cell carcinoma (Case 1) and coexpression of keratin, EMA, synaptophysin, and chromogranin-A, suggesting neuroendocrine neoplasm (Case 2)." (PMID 34228212, 2022). "Traditional markers for neuroendocrine tumors comprise synaptophysin, chromogranin A, and CD56 (NCAM1)." (PMID 34884272, 2021). "With a clinical suspected neuroendocrine tumor, biochemical markers such as chromogranin A and 5-Hydroxyindoleacetic acid were requested." (PMID 34352621, 2021). "Numerous immunoassays have been developed to measure the levels of chromogranin A (CgA), a useful biomarker for diagnosing and monitoring generally heterogeneous neuroendocrine tumors (NETs)." (PMID 34943638, 2021). "Other useful biomarkers for LM diagnosis include CA 19-9 (pancreaticobiliary cancer), chromogranin A (neuroendocrine tumor), CA 15-3 (breast cancer) and CA-125 (germinal tumor)." (PMID 34631555, 2021). "In neuroendocrine tumors, plasma chromogranin A (CgA) is one of the most commonly evaluated biomarkers in patients with neuroendocrine tumors." (PMID 34298822, 2021). "Positive controls demonstrated the presence of Chromogranin A staining in neuroendocrine tumor and normal chromaffin cells from the colon." (PMID 33277238, 2021). "Patients with these tumors are typically symptomatic, often secrete ectopic hormones (e.g., ACTH in 40% of tumors) and, like neuroendocrine tumors of the lung, secrete circulating biomarkers such as chromogranin A and 5-HIAA (metabolite of serotonin)." (PMID 33641055, 2021). "Abnormal values of chromogranin A are related with the presence of neuroendocrine tumors with high sensitivity and specificity." (PMID 34352621, 2021). "Chromogranin A (CgA) is a useful biomarker for diagnosis and monitoring of the extremely heterogeneous neuroendocrine tumors (NETs)." (PMID 34943638, 2021).
neuroendocrine tumors (continued). "Microscopy and immunohistochemistry uncovered a neuroendocrine tumor, staining positive for chromogranin A (CgA), synaptophysin and somatostatin, with a Ki67 = 1%." (PMID 32825782, 2020). "Despite its varying sensitivity and decreased specificity, chromogranin A (CgA) is the most widely used biomarker for neuroendocrine tumors." (PMID 32887459, 2020). "Chromogranin A correlated significantly with potassium in patients with neuroendocrine tumors and there was a significant correlation between ACTH level and severity of hypokalemia." (PMID 33237923, 2020). "As in the case of our patient, such neuroendocrine tumors usually present with liver metastasis since neoplastic cells from the pancreas enter the enterohepatic circulation and plasma chromogranin A (CgA) is usually elevated." (PMID 32903471, 2020). "CHGA is a protein in the secretory granules of several normal and neoplastic neuroendocrine cells, and it has been considered an important biomarker of neuroendocrine neoplasms." (PMID 33209196, 2020). "Expression of CHGA has been proven to be associated with prognosis in CRC, and has been currently accepted as the main biomarker for neuroendocrine neoplasms." (PMID 31207989, 2019). "In this work we present our experiences with radioimmunoassay of plasma chromogranin A (CGA) in the laboratory diagnosis of neuroendocrine tumors classified as pheochromocytoma (PCC) and paraganglioma (PGL)." (PMID 31027285, 2019). "Well differentiated neuroendocrine tumor cells synthesize, store and secrete chromogranin A (CGA) and amines; metastatic neuroendocrine carcinomas have fewer cytoplasmic secretory granules." (PMID 31027285, 2019). "CHGA was considered as a biomarker for neuroendocrine neoplasms and was approved, with microarrays and tissue arrays, as a potential biomarker for early cancer diagnosis of gastric cancer and prostate cancer." (PMID 31207989, 2019). "The clinical characteristics of our NEPC patient cohort are in line with previous reports, including the frequent presence of visceral metastases and paraneoplastic syndromes, as well as elevated neuroendocrine tumor markers (chromogranin A, NSE)." (PMID 30713600, 2019). "Pathological examination and immunohistochemical stainings such as chromogranin A, synaptophysin and Ki-67 are required for the diagnosis of a neuroendocrine neoplasm." (PMID 31731083, 2019). "The majority of pancreatic neuroendocrine tumors showed CHGA positive immunostaining, and primary tumors with metastases revealed significantly less CHGA protein expression than primary tumors without metastases." (PMID 31207989, 2019). "Chromogranin A is a widely used biomarker for the assessment of neuroendocrine neoplasms, especially for the diagnosis and management of those of gastroenteropancreatic origin." (PMID 30057604, 2018). "Chromogranin A (CgA) is a plasma biomarker widely used in the follow-up of patients with neuroendocrine neoplasms (NENs)." (PMID 29723285, 2018). "Chromogranin A and synaptophysin expression is seen in 69.1 and 90.2%, respectively, of gastroenteropancreatic neuroendocrine neoplasms." (PMID 29740725, 2018). "Chromogranin A, called secretagranin I, is from a group of proteins present in several neuroendocrine tissues, and is a good marker for both neuroendocrine tumors and pancreatic islet cell carcinoma, as well as multiple endocrine neoplasia." (PMID 29324681, 2018). "Chromogranin A, a protein secreted from secretory granules in neuroendocrine cells, has become a standard biomarker in patients with neuroendocrine tumors despite having only limited utility." (PMID 28903345, 2017). "Chromogranin A, a protein secreted by neuroendocrine cells, is a commonly used biomarker in patients with neuroendocrine tumors and can be obtained at diagnosis or in follow up of patients with resected or metastatic disease." (PMID 28903345, 2017).